CDK4 (cyclin dependent kinase 4)
Diseases named in the same sentence as CDK4 in open-access papers (continued):
Sharing a sentence is not in itself a finding about the gene and the disease.
breast cancer (continued). "While clinical studies have focused predominantly on the use of CDK4/6 inhibitors to treat endocrine-resistant breast cancer, and use of CDK2/1 inhibitors has also been considered." (PMID 35441158, 2022). "The sequential combination of abemaciclib following eribulin merits further clinical trials to overcome resistance to CDK4/6 inhibitors in HR-positive breast cancer." (PMID 35008374, 2022). "In advanced HR-positive, HER2-negative breast cancers, the addition of cyclin-dependent kinases 4 and 6 (CDK4/6) inhibitors has become the new standard of care." (PMID 35813042, 2022). "In second‐line treatment, CDK4/6 inhibitors combined with the selective estrogen receptor degrader fulvestrant for HR‐positive/HER2‐negative breast cancer were studied in three trials: PALOMA‐3, MONALEESA‐3, and MONARCH‐2." (PMID 36254250, 2022). "A better understanding of resistance mechanisms is essential for the development of optimal management strategies when breast cancer patients are treated using CDK4/6 inhibitors." (PMID 35740538, 2022). "The essential role of CDKs in promoting cell cycle progression (through phosphorylation of Retinoblastoma (Rb)) established CDK4/6Is as a selective target therapy to influence outcomes in breast cancer, especially therapy-resistant breast cancer." (PMID 36358806, 2022). "Among the three CDK4/6 inhibitors, abemaciclib is the only one that shows promising efficacy as a single agent to treat HR+ breast cancer." (PMID 35892870, 2022). "The CDK4/6–DUB3 axis promotes breast cancer metastasis, serving as a promising therapeutic target for the treatment of breast cancer." (PMID 35383144, 2022). "The FDA has already approved three CDK4/6 inhibitors for lifelong breast cancer therapy (palbociclib, abemaciclib, ribociclib), which mainly work by avoiding the G1 to S cell-cycle phase transition." (PMID 35681689, 2022). "This sequential combination of abemaciclib following eribulin merits further clinical trials to overcome resistance to CDK4/6 inhibitors in HR-positive breast cancer." (PMID 35008374, 2022). "The success of CDK4/6 inhibitors in ER + breast cancer is driven by the interplay between estrogen and CDK4/6 signaling." (PMID 35974168, 2022). "The present studies demonstrated that GZ17-6.02 interacted with the CDK4/6 inhibitor palbociclib to kill ER+ breast cancer cells." (PMID 35035775, 2022). "Combination of palbociclib with PI3K/mTOR inhibitor in pancreatic cancer and combination of CDK4/6 inhibitor with PI3Kα inhibitor in breast cancer also leads to apoptosis." (PMID 35327487, 2022). "Noticeably, among all CDK4/6 inhibitors analyzed, which are newly approved as first line drugs in breast cancer in recent years, the IC50 of Palbociclib, and Ribociclib were positively correlated with the risk score." (PMID 36358783, 2022). "Blocking the PFKFB3–CDK4 interaction improves the therapeutic effect of the FDA-approved CDK4 inhibitor palbociclib against breast cancer." (PMID 36059650, 2022). "Typically reserved for advanced breast cancer following CDK4/6 inhibitor resistance, PI3K-alpha inhibitors have been observed clinically and in cell line data to be ineffective when used in PTEN-null cells." (PMID 35685436, 2022). "Several CDK inhibitors were developed, among which the CDK4/6 inhibitors palbociclib, ribociclib, and abemaciclib were recommended as vital components of systemic therapy for HR+ breast cancer." (PMID 36145516, 2022). "Another study in breast cancer patients has indicated better progression-free survival time in those treated with CDK4/6 inhibitors than those received PI3K inhibitors." (PMID 36266723, 2022). "Functionally, Id2 promotes a low proliferative indolent state in lobular breast cancer cells through inhibition of CDK4/6-Rb-dependent cell cycle progression, enabling anchorage independence and subsequent metastatic dissemination." (PMID 35437308, 2022).
breast cancer (continued). "The CDKIs that are currently FDA-approved for breast cancer therapy are oral agents that selectively inhibit CDK4 and CDK6, include palbociclib (Ibrance), ribociclib (Kisqali), and abemaciclib (Verzenio)." (PMID 36358806, 2022). "Resistance to aromatase inhibitor (AI) treatment and combined CDK4/6 inhibitor (CDK4/6i) and endocrine therapy (ET) are crucial clinical challenges in treating estrogen receptor-positive (ER+) breast cancer." (PMID 36153348, 2022). "Currently, although combination therapy of endocrine therapy plus CDK4/6 inhibitors remains the standard first‐line treatment for patients with HR‐positive/HER2‐negative advanced breast cancer, drug resistance still needs to be addressed." (PMID 38089455, 2022). "In preclinical experiments, abemaciclib is a potent, selective cell growth inhibitor, inhibiting preferentially the CDK4/Cyclin D1 complex and leading to cell senescence and cell death in breast cancer cell lines with broad molecular profiles." (PMID 35813283, 2022). "Breast cancer cells treated with palbociclib have shown drug resistance because CDK2 takes the roll of CDK4." (PMID 35327487, 2022). "High CDK4 and CDK6 expression were also observed in CDK4/6 inhibitors (CDK4/6i)-resistant glioblastoma multiforme xenograft and ER+ breast cancer cell line models separately." (PMID 35327487, 2022). "Perhaps it is an amenable elucidation for the combination of CDK4/6 with immunotherapy or with endocrine therapy to be an appealing strategy in the treatment of patients with breast cancer." (PMID 35764927, 2022). "Previously, we reported the anti‐apoptotic role of cytoplasmic p21 in CDK4/6 inhibitor‐induced senescent breast cancer cells." (PMID 36054146, 2022). "In contrast, the agents recently approved by the FDA for use in breast cancer are oral highly selective inhibitors of CDK4/6 and include palbociclib, ribociclib, and abemaciclib." (PMID 35530846, 2022). "It is the only CDK4/6 inhibitor licensed with fulvestrant as a first- or second-line therapy for postmenopausal women with HR+/HER-positive advanced breast cancer." (PMID 35530846, 2022). "In the neoadjuvant setting, oral SERDs are being explored in locally advanced HR + /HER2 − stage III breast cancer against AIs alone as in AMEERA-4 (amcenestrant) or in combination with CDK4/6 inhibitors as in coopERA BC study (giredestrant)." (PMID 36229710, 2022). "New evidence on the impact of dysregulation of the CDK4/6 pathway on breast cancer (BC) cell proliferation has led to the development of selective CDK4/6 inhibitors, which have radically changed the management of advanced BC." (PMID 36498861, 2022). "As a result, the onset and incidence of mammary carcinoma in MMTV-Neu-Cdk4−/− mice are delayed and substantially reduced, respectively." (PMID 36051751, 2022). "Of note, the HER2-positive breast cancer cell line tended to be the most sensitive to miRNA and CDK4/6 inhibitor combination." (PMID 34439268, 2021). "The combination of CDK4/6i with endocrine therapy is now standard-of-care first-line therapy for advanced breast cancer." (PMID 33671468, 2021). "Recent preclinical studies reported cross-resistance between the three approved CDK4/6i in palbociclib-resistant breast cancer cell models." (PMID 34771560, 2021). "The relevance of comprehensive geriatric assessments to guide CDK4 and 6 inhibitor treatment plans in older patients with breast cancer has also been noted." (PMID 33392835, 2021). "Palbociclib, abemaciclib and ribociclib are the CDK4/6 inhibitors approved in combination treatments for estrogen receptor positive (ER+) breast cancers." (PMID 34686682, 2021). "Many mechanisms of how breast cancer cells can become resistant to CDK4/6 inhibitors are known at this point, and more are constantly being discovered." (PMID 34830174, 2021).
breast cancer (continued). "Remarkably, employment of D 4476 potentiates the efficacy of ribociclib in inhibiting RB1 phosphorylation in multiple CDK4/6i resistant breast cancer cells, accompanied with antagonizing CDK4/6i treatment induced CDK6 protein accumulation." (PMID 34508104, 2021). "Breast cancer cells acquire ESR1 mutation following exposure to ET, particularly an AI, and also in combination with CDK4/6i." (PMID 34771560, 2021). "In line with previous studies, our analysis of clinical data revealed that CDK2/CDK4 are overexpressed in breast cancer patients and contribute to tumor progression, metastasis, invasive phenotypes and non-responsiveness to chemotherapy." (PMID 34421361, 2021). "The CDK4/6-Rb interaction increases cancer cells' survival and CDK4/6 is known to play a role in breast cancer pathogenesis and tumorigenesis." (PMID 34729098, 2021). "In a preclinical model of breast cancer using an ER+ cell line (MCF-7), the overexpression of FGFR1 causes a resistance to treatment with fulvestrant and a CDK4/6 inhibitor, either palbociclib or ribociclib." (PMID 33535617, 2021). "USP51 has been demonstrated as a deubiquitinase of ZEB1 in breast cancer cells, and its catalytic activity is induced by phosphorylation of CDK4/6." (PMID 34575114, 2021). "For instance, the combination of HCQ + Abemaciclib (CDK4/6 inhibitor) +/− endocrine therapy suggests a positive outcome for clinical trial in HR-positive/HER2- breast cancer lesions (NCT04316169)." (PMID 34207792, 2021). "miR-326 conferred sensitivity to treatment with CDK4/6 inhibitor ribociclib in HER2-positive breast cancer cell lines." (PMID 34439268, 2021). "While CDK4/6 inhibitors have proven to be highly effective in the clinic for ER+ breast cancer patients, de novo or developed resistance to these drugs is common." (PMID 34830174, 2021). "We have recently found activation of the cyclin E-CDK2 axis in both breast cancer cell models resistant to AI monotherapy and combined CDK4/6i with fulvestrant." (PMID 34771560, 2021). "Given the success of CDK4/6 inhibitors in advanced ER+ breast cancer, trials are underway to expand the use of this treatment modality against TNBC." (PMID 33599863, 2021). "The mammalian target of rapamycin (mTOR) inhibitor—everolimus—and the CDK4/6 inhibitors—palbociclib and ribociclib—have been approved to treat breast cancer patients who are HER2-negative and hormone receptor (HR)-positive." (PMID 35056985, 2021). "Another study has shown that loss of PTEN mediates overexpression of activated AKT, CDK4, and CDK2 in CDK4/6i-resistant breast cancer cell models." (PMID 34771560, 2021). "This structural diversity provides useful information for active inhibition which helped to develop new CDK4/6-selective inhibitors to be registered for clinical use in breast cancer treatment." (PMID 33805800, 2021). "A phase III clinical trial, the SONIA study (NCT03425838), is investigating the best use of CDK4/6 inhibitors in patients with HR+/HER2- advanced breast cancer." (PMID 34830174, 2021). "A high throughput in vitro siRNA screen in breast cancer cells identified that PDK1 knockdown increases the sensitivity of cells to CDK4/6 inhibition." (PMID 34830174, 2021). "In comparison, our MCF7-LTED and T47D-LTED breast cancer cell models represent acquired endocrine resistant breast cancer that are intrinsically resistant to CDK4/6 inhibitors, which comprises about 20% of breast cancer patients in the clinic." (PMID 34277427, 2021). "In an in vitro experiment, CDK4 inhibitor (PD-0332991) reduced cell tumor growth of fulvestrant-insensitive ER+ cell lines and tumor growth of mice bearing an ER+ breast cancer cell line." (PMID 33477469, 2021).
breast cancer (continued). "The success of CDK4 inhibitors in combination with endocrine therapy in breast cancer patients has encouraged investigations into the role of CDK4 inhibitors in other cancer types, including lung cancer." (PMID 34309585, 2021). "While ER+ MCF7 breast cancer cells are at least partly dependent on CDK4/6 activity for cell cycle entry, p21/p27 appear to mediate their palbociclib sensitivity." (PMID 34784791, 2021). "Less is known of the associations between common genomic aberrations in advanced ER+ breast cancer and clinical outcome, particularly in the updated therapeutic landscape that includes combination CDK4/6i treatments." (PMID 32940689, 2021). "Approximately 35% of ERα+ breast cancers demonstrated amplification of CCND1 gene (encoding cyclin-D1), and about 16% demonstrated amplification of the gene that encodes CDK4." (PMID 33498407, 2021). "Here, we used endocrine sensitive ER+ MCF7 and T47D breast cancer cells to generate long-term estrogen deprived (LTED) endocrine resistant cells that are intrinsically resistant to CDK4/6 inhibitors." (PMID 34277427, 2021). "Increased levels of activated AKT were also reported in combined palbociclib and fulvestrant-resistant breast cancer cell models and were significantly associated with low PFS in ER+/HER2− ABC patients treated with combined CDK4/6I and ET." (PMID 34771560, 2021). "The unexpected and impressive activity reported for palbociclib in breast cancer patients when used in combination with anti-estrogen therapy then rapidly stimulated the design of other CDK4/6 inhibitors that rapidly entered in clinical development." (PMID 34204543, 2021). "Loss of RB expression is a commonly used criterion to exclude or include patients with advanced ER+ breast cancer on clinical trials with CDK4/6 inhibitors." (PMID 34277427, 2021). "Though this clinical trial did not include a control group for comparison of efficacy, it was determined that combination therapy with alpelisib is useful in ER+ breast cancer patients whose tumors progressed while on CDK4/6 inhibitors." (PMID 34830174, 2021). "In this study, we used ER+ endocrine sensitive breast cancer cells, MCF7 and T47D, to generate long-term estrogen deprived (LTED) endocrine resistant breast cancer cells that are intrinsically resistant to CDK4/6 inhibitors." (PMID 34277427, 2021). "Pyrotinib is a pan-her kinase inhibitor that can be used in HER2-positive tumors, while SHR6390 is a CDK4/6 inhibitor that can inhibit ER+ breast cancer cell cycle progression and cancer cell proliferation." (PMID 34977029, 2021). "These sequencing data became more robust in the 2000s with the availability of the Cancer Genome Atlas, which elucidated that aberrations leading to hyperactivation of CCND1/CDK4/6 were specifically common in ER+ breast cancer subtypes." (PMID 34771508, 2021). "Endocrine treatment plus CDK4/6 inhibitors have become standard of care for estrogen receptor positive (ER+) breast cancer." (PMID 33634015, 2021). "Data from PALOMA-2 reinforced ER status as a significant marker for therapeutic benefit with observations supporting that this breast cancer subtype is dependent on the CDK4/6:cyclin D:retinoblastoma pathway." (PMID 34698970, 2021). "The same trend of the result was also demonstrated in HT29 colorectal cancer cells, MCF-7 breast cancer cells, and human ovarian cancer cells with downregulation of cyclin D1 and CDK4." (PMID 33507701, 2021). "Current Japanese Breast Cancer Society Clinical Practice guidelines recommend a CDK4/6 inhibitor plus an aromatase inhibitor as a first-line endocrine therapy for postmenopausal patients with HR+/HER2‒ ABC." (PMID 34698970, 2021). "A recent study further revealed that loss of PTEN expression is a mechanism of adaptive resistance to CDK4/6i in breast cancer patients." (PMID 33809714, 2021).
breast cancer (continued). "Although inhibitors targeting CDK4/6 kinases (CDK4/6i) have shown promising clinical prospect in treating ER+/HER2- breast cancers, acquired drug resistance is frequently observed and mechanistic knowledge is needed to harness their full clinical potential." (PMID 34508104, 2021). "CDK4/6 inhibitors (CDK4/6i) are effective in treating several cancers, such as breast cancer and melanoma." (PMID 34459131, 2021). "Breast cancer cells resistant to CDK4/6 inhibitors show upregulation of cystatin S and alpha B-crystallin." (PMID 34830174, 2021). "p-AKT levels in full sections of metastatic lesions of ER+breast cancer patients treated with combined endocrine therapy and CDK4/6i in the advanced setting were evaluated by immunohistochemistry." (PMID 34433817, 2021). "Recently, models of ER+ breast cancer cells are being explored to elucidate resistant mechanisms in order to identify targeted therapies for endocrine and CDK4/6 inhibitors resistant breast tumors." (PMID 34277427, 2021). "Palbociclib, a CDK4/6 inhibitor (CDKi), is in phase 3 clinical trials for the treatment of ER-positive advanced breast cancer." (PMID 33986665, 2021). "Cyclin-dependent kinase 4/6 inhibitors represent a major advance in breast cancer treatment, emerging as the standard of care of the initial treatment of hormone receptor-positive and HER2-negative metastatic breast cancer." (PMID 34458177, 2021). "The progression-free survival rate of patients with estrogen receptor-positive breast cancer can improve when CDK4/6 inhibitors are added to antiestrogen therapy." (PMID 33868991, 2021). "In ER+ breast cancer cells that are resistant to CDK4/6 inhibitors, the mammalian target of rapamycin (mTOR) pathway is commonly mutated." (PMID 34830174, 2021). "For instance, CDK4/6 inhibitors are providing survival benefit to the certain types of breast cancer characterized by G0/G1 acceleration induced by the CDK4/6-RB1 pathway." (PMID 34513922, 2021). "A screening of 47 breast cancer cell lines revealed that CDK4/6 inhibition suppresses the growth of ER+ luminal cancer and HER2+ cancer cell lines by inhibiting RB phosphorylation." (PMID 33809714, 2021). "Future studies need to compare the PFS and response rates in patients given this combination to patients given CDK4/6 inhibitor monotherapy to evaluate if it is a viable method of prolonging resistance to CDK4/6 inhibitors in breast cancer patients." (PMID 34830174, 2021). "Activation of the PI3K-AKT-mTOR pathway or cell-cycle promoter CDK4/6 has been shown to be important as the mechanism of how breast cancer acquires resistance to endocrine therapy." (PMID 34070471, 2021). "Several studies have demonstrated that CDK4 is upregulated in cancer and inhibiting CDK4 expression increases the efficacy of clinical treatments for breast cancer, melanoma, liposarcoma, and mantle cell lymphoma." (PMID 33968776, 2021). "Systemic treatment of hormone receptor-positive (HR+) breast cancer is undergoing a renaissance, with a number of targeted therapies including CDK4/6, mTOR, and PI3K inhibitors now approved for use in combination with endocrine therapies." (PMID 33671468, 2021). "As a proof-of-concept, focused follow-up studies silencing either RB1 or CDK6 led to significant alteration of drug sensitivity of MCF7 breast cancer cells to CDK4/6i, supporting the reliability of our in vitro screening results." (PMID 34508104, 2021). "In the future, the role of CDK4/6 inhibitors, as well as other target treatments, will probably extend NET indications to high-risk ER+ breast cancer patients." (PMID 34064183, 2021). "Here, we obtained paired plasma samples at baseline and week 4 in 45 consecutive patients with advanced breast cancer treated with CDK4/6i+ET." (PMID 33536433, 2021). "Cytoplasmic p21, which was increased in CDK4/6 inhibitor‐induced senescent cancer cells, can protect human breast cancer cells from apoptosis." (PMID 34761877, 2021).